NF1 (neurofibromin 1)
Diseases named in the same sentence as NF1 in open-access papers (continued):
Sharing a sentence is not in itself a finding about the gene and the disease.
glioblastoma (189 papers, 2009 to 2026). The most malignant astrocytic tumor (WHO grade IV). "NF1 mutations are generally seen in 13% of glioblastoma patients, notably in the mesenchymal subtype of primary glioblastoma." (PMID 41212363, 2025). "Several prognostic features were characterized, including NF1 alteration and 21q loss in glioblastoma, and EGFR amplification and 22q loss in IDH1/2-mutant astrocytoma." (PMID 39164213, 2025). "NF1 is recurrently mutated in glioblastoma, yet the availability and efficacy of targeted therapies leveraging this genetic alteration are limited." (PMID 40985888, 2025). "NF1 mutations are primarily associated with the mesenchymal glioblastoma subtype, and PDGFRA is correlated with the proneural glioma subtype." (PMID 40564017, 2025). "To date, only two case reports of MEK inhibitor therapy among NF-1-associated glioblastoma patients have been described." (PMID 40725122, 2025). "In a separate study, the tool compound Y102 was found to reduce viability across multiple NF1-deficient cell lines, including glioblastoma, pNF, and MPNST models." (PMID 41294711, 2025). "The compound Y100 and its analog, Y100B, were shown to reduce cell viability in at least two NF1-deficient glioblastoma cell lines." (PMID 41294711, 2025). "In a 19-year-old male receiving trametinib as a fourth-line treatment for NF-1-associated glioblastoma, a complete response was achieved at 10 months, which was noted to be sustained at a 13-month clinic visit." (PMID 40725122, 2025). "On multivariable CPH analysis incorporating significant clinical variables, CDKN2A/B loss was the only genetic co-alteration that remained significantly associated with worse OS in NF1-mutant glioblastoma." (PMID 40985888, 2025). "While RAS itself is not typically mutated, the RAS pathway is genetically altered in glioblastoma, astrocytoma, and high- and low-grade glioma, with NF1 loss being quite common in up to 17% of glioblastoma." (PMID 41248180, 2025). "Genomic studies of glioblastoma have associated NF1 mutation with enrichment of mesenchymal-like (MES-like) transcriptional tumor cell state and an altered tumor microenvironment." (PMID 40985888, 2025). "The mesenchymal subtype of glioblastoma, defined by frequent NF1 alterations and low mRNA expression of NF1, is associated with a poor prognosis." (PMID 39472976, 2024). "It is noted that patients with NF1-associated glioblastoma are diagnosed at a significantly younger age (mean age 37 years) compared to those with sporadic glioblastoma (above 55)." (PMID 39211378, 2024). "Here, we report that this patient relapsed with a glioblastoma displaying compound loss of function mutations in NF1, suggesting that the dacomitinib was acting on target, inhibiting EGFR and selecting for EGFR-negative subclones." (PMID 38548752, 2024). "Here, we describe the landscape of NF1 alterations in a large institutional cohort of 542 molecularly profiled IDH-wildtype glioblastomas, identifying clinical and molecular correlates of NF1 loss." (PMID 39472976, 2024). "Over a quarter of the glioblastoma cases mapped to the G3/NF1 and G4/RAF subgroups with oncogenic mutations in the upper segment of the ERK/MAPK signaling cascade." (PMID 38254850, 2024). "A younger age of onset, higher tumor mutation burden and expanded G1/EGFR-mutant and G3/NF1 glioblastoma subgroups characterized the glioblastomas from African American/Black relative to Caucasian/White patients." (PMID 38254850, 2024). "Here, we evaluate the genomic landscape of NF1 alterations in IDH-wildtype glioblastoma, validate an immunohistochemical biomarker for NF1 loss, and identify other immunohistochemical, genomic, and clinical correlates of NF1 immunostaining." (PMID 39472976, 2024).
glioblastoma (continued). "Analysis of a separate institutional cohort of IDH-wildtype glioblastomas also identified NF1 alterations to be associated with decreased overall survival." (PMID 39472976, 2024). "We also show that minimal to absent NF1 immunoreactivity is a poor prognostic marker in IDH-wildtype glioblastoma, but the underlying molecular mechanisms leading to decreased NF1 expression in NF1-wildtype GBM require further investigation." (PMID 39472976, 2024). "Somatic mutations in NF1 also occur in 5% to 10% of human cancers, particularly lung cancer, glioblastoma, and breast cancer, and are associated with resistance to therapy." (PMID 37124503, 2023). "Several studies have reported that part of wt-IDH glioblastomas with NF1 mutation also presented a xanthomatous histological appearance." (PMID 36505786, 2022). "The NF1-associated glioblastoma cell line JHH-NF1-GBM1, which carries an ATRX mutation and exhibits ALT, grows under neurosphere conditions and intracranially as orthotopic xenografts, albeit slowly." (PMID 35740680, 2022). "Only 2/6 of the NF1-associated glioblastomas from our study had the combination of trisomy 7 and monosomy 10, and none harbored TERT promoter mutation or EGFR amplification." (PMID 35945463, 2022). "In glioblastoma, NF1 loss of function plays a major role in inducing the mesenchymal (MES) subtype and, therefore defining the most aggressive glioblastoma." (PMID 35008787, 2021). "It is interesting to note these facts because NF1 gene is inactivated by one of many mechanisms in about 13% of glioblastoma, and NF1 loss is directly correlated with GBM aggressiveness." (PMID 32089990, 2020). "In particular, high grade gliomas (anaplastic, glioblastoma-GBM) are more frequent in adults with NF-1, which have five times greater risk for GBM than the general population." (PMID 33114250, 2020). "Although it is challenging to draw a conclusion based on few case reports, the observed age of occurrence of NF1-associated glioblastoma in adults, mean of 38.3 years, is much younger than the mean age for patients with sporadic glioblastoma." (PMID 31906320, 2020). "Future large scale molecular and natural history studies are required to demystify the NF1-associated glioblastomas and how they relate to sporadic gliomas." (PMID 31906320, 2020). "Multiple genes implicated in cell proliferation and differentiation, including the telomerase reverse transcriptase gene, c-MET, EGFR and NF1, have been showed to be mutated or overly expressed in glioblastoma." (PMID 30787206, 2019). "NF1 loss in glioblastoma is also associated with increased macrophage infiltration displaying pro-tumorigenic features." (PMID 31611871, 2019). "Mesenchymal glioblastoma cells often harbor mutations and/or deletions in the gene encoding neurofibromin 1 (NF1)." (PMID 30823646, 2019). "The NF1 gene is frequently deleted in a mesenchymal type of glioblastoma, but the overall frequency of the NF1 gene deletion/mutation was reported to be around 30% in mesenchymal GBMs, similar to gliosaroma samples." (PMID 30818875, 2019). "Further, the NF1 gene is frequently mutated in various types of sporadic human cancers, including glioblastoma, neuroblastoma, acute myeloid leukemia, as well as lung, ovarian and breast tumors, thus highlighting a broader role for NF1 in human cancer." (PMID 30131853, 2018). "Mutation of NF1 or loss of the NF1 protein is also observed in glioblastoma, lung adenocarcinoma, and ovarian cancer among other sporadic cancers." (PMID 29662612, 2018).
glioblastoma (continued). "We next evaluated the effect of Y100 treatment on NF1 deficient U87-MG and U251-MG glioblastoma cells." (PMID 29662612, 2018). "In 2008, The Cancer Genome Atlas (TCGA) analysis of glioblastoma (GBM) revealed NF1 mutations or other alterations in approximately 20% of sporadic GBM, i.e. in patients without NF12." (PMID 29643433, 2018). "In human cancers, we found evidence for co-loss of neurofibromin and Grb10 expression in human glioblastoma, a tumor type in which NF1 is among the most significantly mutated genes." (PMID 26000738, 2015). "TGF-β3 mRNA levels were higher in patients with tumors with mutations in the NF1 gene, for all patients pooled (p=0.013) and also in patients diagnosed for the mesenchymal glioblastoma subgroup (p=0.03)." (PMID 25849941, 2015). "TGF-β gene and TGF-β target gene expression were increased in glioblastomas with mesenchymal gene expression signature, which is defined by aberrations of the NF1 gene and proposed to be associated with inferior survival." (PMID 25849941, 2015). "This includes deletions of known tumour suppressors such as RB1 and NF1, but also more novel glioblastoma associated genes." (PMID 24548782, 2014). "In glioblastoma, NF1 inactivating mutations were identified from a large panel of sequenced tumors, suggesting NF1’s relevance to the development of sporadic glioblastoma." (PMID 23335975, 2013). "Inactivating NF1 deletions or mutations have recently been shown in 23% of adult glioblastoma patient samples and 6% of pediatric HGG." (PMID 22184287, 2011). "We considered two subtypes of primary glioblastoma: the subtype driven by NF1 loss and the subtype driven by PDGF overexpression." (PMID 21931722, 2011). "In addition, although glioblastoma represents a distinct clinical entity, patients with glioblastoma associated with NF1 have been reported to have better prognoses than those without NF1." (PMID 41216086, 2025). "NF1 mutations were significantly associated with poor prognosis in glioblastoma." (PMID 40564017, 2025). "Glioblastomas that harbor NF1 variants show a specifically poor outcome." (PMID 41168866, 2025). "Similarly, as a fourth-line treatment, trametinib therapy was provided to a 24-year-old male suffering from NF-1-associated glioblastoma on a compassionate care basis." (PMID 40725122, 2025). "Glioblastoma in patients affected by NF1 germline mutation delineates a unique entity." (PMID 40277798, 2025). "Validation studies with a larger cohort of glioblastomas having known mRNA expression levels and genomic status will be necessary to further evaluate this observation and determine the underlying mechanism driving minimal NF1 expression." (PMID 39472976, 2024). "Among Glioblastomas, the NF1 gene was found to be mutated in 20% of these cases." (PMID 38611039, 2024). "The co-occurrence of PTPN11 and NF1 mutations may work together to promote the uncontrolled growth and proliferation of cancer cells in glioblastoma." (PMID 38418494, 2024). "In addition, a variety of other sporadic human tumors are also associated with inactivating mutations in NF1 including glioblastoma, lung adenocarcinoma, acute myeloid leukemia, and ovarian and breast cancers." (PMID 37369741, 2023). "Cell lines derived from NF1-deficient sporadic glioblastomas (U251, SF188), an NF1-associated ATRX mutant glioblastoma cell line (JHH-NF1-GBM1), an NF1-derived sarcoma cell line (JHH-CRC65), and two NF1-deficient MPNST cell lines (ST88-14, NF90.8) were utilized." (PMID 35740680, 2022).
glioblastoma (continued). "The NGS analysis has revealed that patients with grade IV glioblastoma exhibited lesser DNA content in EVs than controls and that, both in EVs and matched cancer tissues, the NF1 gene was consistently mutated in all patients, with the c.2568C>G as the most common pathogenic variant expressed." (PMID 36289852, 2022). "In addition, NF1 is mutated in a variety of other cancers, including lung adenocarcinoma, squamous cell carcinoma, breast and ovarian cancer, glioblastoma, and acute myeloid leukemia." (PMID 33096593, 2020). "A clinicopathologic study that identified five children with NF1-associated glioblastoma indicated better outcomes compared to sporadic glioblastoma, an observation similar to another study that identified four adults with NF1-associated glioblastoma." (PMID 31906320, 2020). "In addition, the glioblastoma mesenchymal subtype that is associated with NF-1 and RB-1 mutations can have significantly increased TIL." (PMID 33202642, 2020). "Also, somatic NF1 mutation has been reported in 5–10% of sporadic tumors like glioblastoma, breast cancer, juvenile myelomonocytic leukemia, and lung adenocarcinoma." (PMID 31906320, 2020). "Although NF1 mutations may occur in glioblastoma in conjunction with other mutations, a fibrillary/piloid, not an epithelioid morphology was associated with them." (PMID 31258848, 2019). "Loss of NF1 expression in glioblastoma is associated with increased aggressiveness of the tumor." (PMID 30967630, 2019). "In addition to these frequent abnormalities, the TCGA study reported the frequent mutations of neurofibromatosis type 1 (NF1) gene, occurring in 23% of glioblastoma patients." (PMID 30279357, 2018). "Given that Y100 and CCCP both have differential activity in wild-type and nf1Δ yeast, and the similar metabolic profile of these molecules on NF1 deficient glioblastoma cells, we postulated that Y100 may be a mitochondrial uncoupler." (PMID 29662612, 2018). "Finally, after performing an analysis of frequently occurring genetic alterations in glioblastoma multiforme, NF1 loss-of-function was significantly associated with strong PD-L1 expression in both TCGA and Freiburg databases." (PMID 28178682, 2017). "Glioblastoma in patients affected by NF1 germline mutation (NF1-associated GBM) represents a unique heterogeneous clinical and pathological entity." (PMID 40277798, 2025). "The data collected showed that the mean age at the diagnosis of patients with NF1-associated high-grade is much younger than that of patients with sporadic glioblastoma (mean age 34 vs. 62 years in GBM-IDHwt-44 years in high-grade astrocytoma-IDHmut)." (PMID 40277798, 2025). "A DL model has been trained on subtypes of glioblastoma that might be of prognostic relevance to represent biologically and clinically low-dimensional representations of cancer gene expression data, which might also be of interest for NF1-associated glioblastoma patients." (PMID 41168866, 2025). "Moreover, the NF1 variant may argue in favor of the presence of HGAP, while NF1 variants can also be found in glioblastomas and pilocytic astrocytomas, among others." (PMID 38345610, 2024). "Notably, 4/6 of the NF1-associated glioblastomas from our study epigenetically aligned with the mesenchymal subclass of glioblastoma, which is the epigenetic subclass that encompasses most sporadic glioblastomas with somatic NF1 inactivation." (PMID 35945463, 2022). "Indeed, there is growing evidence that NF1-associated glioblastoma may comprise a unique subset of glioblastoma IDH wild type." (PMID 31906320, 2020).
glioblastoma (continued). "Mutation of NF1 has also been observed in many sporadic tumor types including lung adenocarcinoma, sporadic MPNSTs, ovarian cancer, and glioblastoma (GBM)." (PMID 29662612, 2018). "Using RNAseq data from The Cancer Genome Atlas (TCGA), we trained an ensemble of 500 logistic regression classifiers that integrates mutation status with whole transcriptomes to predict NF1 inactivation in glioblastoma (GBM)." (PMID 28166733, 2017). "Many aggressive non-NF associated (sporadic) tumors have recently been shown to harbor NF1 mutations, including glioblastoma (GBM), neuroblastoma, melanoma, thyroid, ovarian, breast, and lung cancers." (PMID 28166733, 2017). "Leveraging Nf1-deficient murine M-GBM models, we further demonstrate that Ccl5 shRNA-mediated knockdown increases glioblastoma cell apoptosis in vitro, as well as extends mouse glioblastoma survival in vivo." (PMID 28380429, 2017). "SnRNA-Seq of human NF1-mutant glioblastomas revealed multiple transcriptional tumor cell states within and between patients, linking MES-like cell states to Ras/RAF/MEK activation signatures." (PMID 40985888, 2025). "Taken together, these results highlighted the heterogeneity of NF1-mutant glioblastomas and informed future combination therapies." (PMID 40985888, 2025). "To more broadly understand how NF1 mutation affects glioblastoma cellular populations compared with NF1 wild-type glioblastomas, we next analyzed published glioblastoma snRNA-Seq data comprising both NF1-mutant and NF1 wild-type tumors." (PMID 40985888, 2025). "In aggregate, NF1-mutant glioblastomas were composed of an admixture combining all 4 transcriptional cell states, and OPC-like and MES-like cells were more common than NPC-like or AC-like cells." (PMID 40985888, 2025). "The transcriptional MEK activation signature was significantly increased in MES-like compared with non-MES cells, consistent with human NF1-mutant glioblastoma snRNA-Seq analysis." (PMID 40985888, 2025). "Given prior studies suggest NF1-mutant glioblastomas harbor a distinct microenvironment, we first compared tumor microenvironment cell clusters between NF1-mutant and NF1 wild-type samples." (PMID 40985888, 2025). "We tested the efficacy of the MEK inhibitor selumetinib across 9 glioblastoma cell lines, including 6 NF1-mutant and 3 NF1 wild-type cell lines." (PMID 40985888, 2025). "Single-nucleus RNA sequencing of human patient NF1-mutant glioblastomas demonstrated that mesenchymal-like (MES-like) tumor cells were enriched for MEK activation signatures." (PMID 40985888, 2025). "Regarding NF1, previous cohorts of glioblastoma (TCGA pan-cancer atlas glioblastoma database, MSKCC dataset) have reported approximately a 13% mutation rate for this gene38which is significantly higher than we observed in our cohort (p < 0.01)." (PMID 41044136, 2025). "SnRNA-Seq of human NF1-mutant glioblastoma reveals MES-like cell state correlates with Ras/RAF/MEK activation." (PMID 40985888, 2025). "To complement this analysis and define the response to MEK inhibition in an orthogonal NF1-mutant glioblastoma model, we performed scRNA-Seq of human GBM43 cells treated with vehicle DMSO, selumetinib, or a second MEK inhibitor, trametinib." (PMID 40985888, 2025). "The observed intertumor heterogeneity at the level of DNA alterations and intratumor heterogeneity observed in mouse and human scRNA-Seq data underscore the importance of patient selection within NF1-mutant glioblastomas." (PMID 40985888, 2025). "MES-like cells in NF1-mutant glioblastomas demonstrated significantly increased expression of transcriptional MEK activation and MEK/ERK target gene signatures compared with non-MES cells." (PMID 40985888, 2025).